MTOR (mechanistic target of rapamycin kinase)
Diseases named in the same sentence as MTOR in open-access papers (continued):
Sharing a sentence is not in itself a finding about the gene and the disease.
Insulin resistance (continued). "Improper activation of the tuberous sclerosis complex (TSC)/ Ras homolog enriched in brain (Rheb)/mechanistic target of rapamycin kinase (MTOR) signaling pathway leads to insulin resistance." (PMID 30678306, 2019). "Impaired BCAA catabolism correlates with the occurrence of insulin resistance and muscle hypertrophy through activating the mTOR pathway." (PMID 30626440, 2019). "Serine phosphorylation of the insulin receptor substrate (IRS) is linked to insulin resistance and a number of serine/threonine kinases including JNK, mTOR and p70 S6K have been implicated in this process." (PMID 30400151, 2018). "In order to further confirm pinocembrin's influence on the alleviation of insulin resistance, the phosphorylation of key Akt/mTOR signaling proteins was assayed in insulin-resistant HepG2 cells after pinocembrin treatment." (PMID 30420897, 2018). "Other than indirect effects, there are studies that report direct impact of insulin resistance on autophagy by an inhibition of the downstream mTOR signaling pathway." (PMID 29950970, 2018). "Another study reported that OA stimulates phosphoinositol-3-kinase which phosphorylates Akt and downregulates p-mTOR to improve insulin resistance." (PMID 29596390, 2018). "S6K1 is known to be a downstream effector of mTOR, and to induce insulin resistance via phosphorylation of serine residues of IRS1 as a feedback response." (PMID 29738527, 2018). "Several studies indicate that insulin resistance in T2DM inhibits the downstream mTOR pathway and activates autophagy." (PMID 29950970, 2018). "Women born with highly active ERs, or who suffer from common conditions like polycystic ovary syndrome, are more likely to experience insulin resistance, and the consequent overactivation mTOR." (PMID 29988365, 2018). "Adipocyte-specific mTOR knockout mice have reduced adipose tissue mass, insulin resistance and fatty liver, suggesting its critical role in adipogenesis and systemic energy metabolism." (PMID 30011848, 2018). "In humans, the infusion of amino acids activates the mTOR/S6K1 pathway and consequently causes insulin resistance in skeletal muscles." (PMID 30034573, 2018). "The deletion of S6K1 is sufficient to improve insulin sensitivity in mice and in fat-fed rodents, while the activated mTOR pathway leads to an impaired insulin signaling and insulin resistance." (PMID 30034573, 2018). "NAFLD pathogenesis is considered to be associated with the mammalian target of rapamycin (mTOR) signaling pathway.NAFLD is a manifestation of systemic insulin resistance, and mTOR and S6K1 are key components of the insulin signaling pathway." (PMID 29743930, 2018). "Ultimately, insulin resistance due to elevated mTOR activity, characterized by increased hepatic gluconeogenesis, reduced glucose uptake by muscles, and pancreatic β-cell apoptosis, leads to type II diabetes." (PMID 30034573, 2018). "This study suggests that vaspin can indeed act on the mTOR/p70S6K signaling pathway to improve insulin resistance." (PMID 29240812, 2017). "Phosphatidylinositol 3-kinase (PI3K)/Akt/mTOR pathway was a link between insulin resistance and autophagy." (PMID 29318158, 2017). "AMPK activation triggered a progressive reduction of mTOR activity and showed a protective effect against palmitate induced insulin resistance." (PMID 28706950, 2017). "It has been suggested that high protein intake induces insulin resistance via leucine-mediated activation of the mechanistic target of rapamycin (mTOR)." (PMID 28713581, 2017). "A likely potential common point in insulin resistance in these diseases is a reduced Akt signalling resulting in lower activation of mTOR and eNOS." (PMID 29104874, 2017). "In conclusion, RBPP-P protected the liver from steatosis and insulin resistance in mice with diet-induced obesity by the stimulation of autophagy via the AMPK/mTOR-dependent signaling pathway." (PMID 28452943, 2017).
Insulin resistance (continued). "It was demonstrated that the chronic activation of mTOR by high glucose results in insulin resistance and the hyperactivation of mTOR is involved in diabetic complications." (PMID 28489581, 2017). "It is well known that the mTOR/p70S6K signaling pathway is involved in the pathogenesis of insulin resistance." (PMID 29240812, 2017). "In summary, the present ISN model permits to investigate the insulin signaling network in the insulin resistance states and in cancer, focusing on the role played by Akt phosphorylated at Ser473 and by the mTOR complexes, as well as on the drug effects." (PMID 27149630, 2016). "The purpose of this study was to investigate the effect of exercise and dietary change on obesity and insulin resistance and mTOR signaling protein levels in skeletal muscles of obese rats." (PMID 27508151, 2016). "In summary, despite the negative impact of continuous high fat intake, regular exercise and dietary change showed a positive effect on insulin resistance and mTOR signaling protein levels." (PMID 27508151, 2016). "Previous studies have reported that regular exercise has positive effects on insulin resistance in skeletal muscle via mTOR signaling pathway." (PMID 27508151, 2016). "All these evidences revealed that insulin resistance, adipocytokines and mTOR signal pathway were involved the pathological mechanism of chronic kidney disease." (PMID 27775022, 2016). "Activation of the mTOR pathway results in phosphorylation of several residues of the IRS-1 protein, which can cause insulin resistance." (PMID 25973388, 2015). "To investigate the molecular link between inflammatory stress and insulin resistance, we investigated the role of the mTOR/S6K pathway on insulin signaling." (PMID 26449763, 2015). "At present, convincing evidence suggests that leucine benefits protein synthesis and improves insulin resistance and insulin sensitivity mainly through the mammalian target of rapamycin (mTOR) pathway." (PMID 26115673, 2015). "In mature and differentiated cells, SIRT1 can prevent insulin resistance through a number of mechanisms that involve fat mobilization, mTOR signaling, and control of cellular inflammation." (PMID 26064426, 2015). "Although SIRT1 can increase cell survival and preserve insulin signaling by blocking apoptotic pathways, SIRT1 also can foster autophagy and limit mTOR activation to preserve mitochondria, promote stem cell proliferation, and prevent insulin resistance." (PMID 26064426, 2015). "Metformin also markedly decreased serum levels of insulin and reduced insulin resistance, and inhibited phosphorylation of Akt, mammalian target of rapamycin (mTOR), and p70S6 in the liver." (PMID 25879666, 2015). "Metformin, an oral antidiabetic drug that suppresses insulin resistance, functions as a growth inhibitor of epithelial cells by reducing mTOR activity 42–44." (PMID 25644309, 2015). "Our results suggest that the combination therapy stimulates PI3K, which phosphorylates AKT and downregulates p-mTOR to improve insulin resistance." (PMID 25789330, 2015). "Insulin resistance is closely related to inflammatory stress and the mammalian target of rapamycin/S6 kinase (mTOR/S6K) pathway." (PMID 26449763, 2015). "From a collective body of work, mTOR/S6K signaling has emerged as a key player in insulin resistance resulting from a variety of conditions, including excessive nutrients and hyperinsulinemia." (PMID 26449763, 2015). "Metabolic syndrome (MetS) is characterized by central obesity and insulin resistance; little is known about how MetS affects the sensitivity of the mTOR pathway to feeding." (PMID 25302072, 2014). "Protein-rich diets have been shown to induce insulin resistance probably through activation of mTOR and S6K signaling pathway." (PMID 25055153, 2014).
Insulin resistance (continued). "High doses of steroids, increase insulin resistance and certain immunosuppressive agents used to treat GVHD (such as calcineurin and mTOR inhibitors) inhibit insulin secretion and/or modulate insulin resistance." (PMID 25496809, 2014). "These adverse metabolic effects suggest that inhibitors of the PI3K/Akt/mTOR pathway contribute to insulin resistance in normal cells." (PMID 25334061, 2014). "This study used obese/diabetic mice and adipocyte culture in vitro to investigate how evodiamine affects glucose tolerance and insulin resistance, especially from the viewpoint of signal transduction, including the mTOR-S6K signaling pathway." (PMID 24391749, 2013). "Ang II promotes insulin resistance and inhibits insulin metabolic signalling by activating mTOR and thus promoting S6K1-mediated IRS-1 serine phosphorylation." (PMID 24400038, 2013). "Leucine activates mTOR pathways that can inhibit early steps in insulin signaling pathways, leading to insulin resistance." (PMID 24023709, 2013). "This pathway can induce insulin resistance and modulate cell proliferation and angiogenesis in response to specific fatty acids, and membrane cholesterol also seems to be necessary for mTOR signalling." (PMID 24135873, 2013). "Conversely, decreased rictor–mTOR and increased raptor–mTOR interaction were noted under insulin-resistance conditions." (PMID 23696823, 2013). "Although it has been proposed that BCAAs drive some of the insulin resistance phenotype through activation of mTOR under high fat feeding conditions or in human obesity, this remains controversial." (PMID 23527196, 2013). "Palmitic acid (16:0) induces insulin resistance through activation of mTOR in skeletal muscle cells and hepatocytes, and a high-fat diet also induced insulin resistance in skeletal muscle in rats by mTOR activation." (PMID 24135873, 2013). "Inhibitors of mTOR would therefore be expected to prevent development of insulin resistance through this mechanism." (PMID 24151517, 2013). "In several studies on animals with insulin resistance induced by high-fat diet, activation of mTOR has been observed." (PMID 22969728, 2012). "In contrast, mTOR inhibition during rapamycin application leads to insulin resistance, reduces β-cell function and mass, limits insulin secretion, and results in DM." (PMID 22545721, 2012). "As upstream physiological counter-regulators of mTOR, lipid-induced mTOR activation and insulin resistance were restored to normal by activated AMPK in both in vivo rat skeletal muscle and hepatocytes." (PMID 22623960, 2012). "This suggests that at the level of AKT/mTOR signaling, fibroblast cells obtained from steatosis patients phenocopy features of insulin resistance." (PMID 22969728, 2012). "Lipid-induced mTOR activation and insulin resistance in rat skeletal muscle were reversed by improved muscle AMPK activation." (PMID 22623960, 2012). "In patients with MetS, we found a reduction of mTOR and other mTOR-related molecules involved in insulin resistance, cell repair, coagulation and vasculogenesis." (PMID 20809949, 2010). "As expected from our analysis of how insulin resistance affected the basal phosophorylation of p70S6k, mTOR and Akt, we found a higher level of basal PTEN phosphorylation in the obese Zucker plantaris muscle compared to that observed in lean animals." (PMID 20368999, 2009). "While the work from Lee, Shan, and colleagues suggests an inhibitory effect of mTOR signaling on WAT browning, both studies argue that adipose-specific inhibition of mTOR or mTORC1 results in lipodystrophy and systemic insulin resistance during postnatal growth." (PMID 41525413, 2026). "On the other hand, due to the key role of insulin signaling in mTOR activation, some studies suggest that omega‐3 therapy may decrease insulin resistance." (PMID 41473401, 2026).
Insulin resistance (continued). "BCAAs have been established as activators of nuclear factor kappa-light-chain-enhancer of activated B cells (NF-kB) mediated inflammatory signaling, as well as contributing to insulin resistance through activation of mammalian target of rapamycin (mTOR) complex-1." (PMID 40564077, 2025). "The deficiency of vitamins like thiamine and pyridoxine may result in increased plasma BCAA levels and, initiate the activation of mTOR/P70S6k and induce the development of insulin resistance." (PMID 39791169, 2025). "Moreover, the mTOR signaling pathway also plays a crucial role in metabolism and cell-cycle regulation; disruption of this pathway leads to insulin resistance and long-term diseases." (PMID 40388307, 2025). "Studies have shown that BCAAs promote insulin resistance, with mTOR as one of the key mechanisms." (PMID 41169508, 2025). "The lower expression of mTOR may indicate its role in reducing insulin resistance in the SW033291-treated group." (PMID 40643509, 2025). "This suggests a pathological cascade: ​​aberrant enzymes involved in BCAA metabolism → BCAA accumulation in the blood → lysosomal activation of the mTOR signalling pathway → elevated androgen levels → insulin resistance and dyslipidaemia → ultimately leading to PCOS​​." (PMID 40687583, 2025). "By influencing mTOR signaling, vitamin D may help counteract excessive fat accumulation and mitigate insulin resistance, playing a protective role in metabolic health." (PMID 40076782, 2025). "Monitoring mTOR activation over time could help determine whether its upregulation in GDM-I placentas is an early compensatory response to insulin resistance or a progressive adaptation that exacerbates fetal overgrowth." (PMID 40136665, 2025). "Additionally, cytokines such as IL-6 can induce insulin resistance, which hinders the activation of the anabolic Akt/mTOR pathway and consequently impairs muscle protein synthesis." (PMID 41573389, 2025). "Several reports documented that, independent of insulin signaling, glucose activates mTOR, which in turn, has a negative feedback loop, blocking the insulin-dependent signaling pathway causing insulin resistance." (PMID 40277891, 2025). "Omega-3 PUFAs may promote muscle anabolism through activation of the mammalian target of rapamycin (mTOR) signaling and reduction of insulin resistance." (PMID 38966419, 2024). "Targeting the mTOR pathway and Klotho protein overexpression could also provide novel strategies to manage hyperglycemia and insulin resistance in GD." (PMID 39519193, 2024). "Metformin can be used to reverse insulin resistance induced by mTOR inhibitors." (PMID 39177917, 2024). "Indeed, several pathways are enhanced, such as an attenuation of pro-inflammatory oxidative stress, mitochondrial function, activation of the mammalian target of rapamycin (mTOR) signaling and reduction of insulin resistance." (PMID 38966419, 2024). "In addition, AMPK and mTOR phosphorylation were analyzed to investigate the effect of leaf, stem, and root decoction extracts on palmitate-induced insulin resistance in L6 cells." (PMID 39795155, 2024). "While systemic mTOR inhibition has been demonstrated to extend lifespan in multiple model organisms and improve many age‐related diseases, this treatment regimen also induces glucose intolerance due to elevated insulin resistance and hepatic gluconeogenesis." (PMID 38017701, 2024). "Furthermore, diet-induced obese mice that express the mutant mTOR-Ser2159Ala share phenotypic similarities as mice with specific inactivation of mTOR complexes, including exacerbated hyperglycemia and systemic insulin resistance." (PMID 38270460, 2024). "The observed results revealed that the plant extract could exert an insulin-resistance alleviation effect through the impairment of the mTOR/p70 S6K signaling pathway." (PMID 39795155, 2024).
Insulin resistance (continued). "Differential metabolites between the model group and the EB-H treatment group were mainly involved in purine metabolism, cytochrome P450, caffeine metabolism, arginine and proline metabolism, the mTOR signalling pathway, insulin resistance, and glycerophospholipid metabolism." (PMID 38611823, 2024). "Moreover, obesity is closely linked to insulin resistance and hyperinsulinemia, which lead to increased IGF-1 levels, activating the PI3K/AKT/mTOR pathway, which is frequently dysregulated in HCC." (PMID 37834153, 2023). "Studies have shown that the dysregulation of mTOR signaling can lead to insulin resistance and impaired glucose metabolism, which are key hallmarks of T2D, in addition to exacerbating the complications associated with the disease, such as cardiovascular disease and diabetic nephropathy." (PMID 37830621, 2023). "PRR5 (mapped with cg008870527) is a component of the (mTOR) complex 2 which is upstream of major pathways known to have a crucial role in metabolic regulation and is suggested to play a role in obesity and the pathogenesis of insulin resistance." (PMID 37649101, 2023). "Several studies have indicated hyperactivation of the mammalian target of rapamycin (mTOR), specifically complex 1 (mTORC1), as a critical mediator of T2D pathophysiology by promoting insulin resistance, hyperlipidemia, inflammation, vasoconstriction, and stress." (PMID 37894760, 2023). "Increased evidences have suggested that excessive accumulation of BCAAs could lead to hyperactivation of the mTOR signalling pathway, induction of oxidative stress, insulin resistance, and/or impaired glucose metabolism." (PMID 36916818, 2023). "BCAA overload may activate the mTOR pathway and inhibit the PI3K-Akt intracellular pathway, causing insulin resistance." (PMID 37781128, 2023). "Overexpression of let-7 causes insulin resistance and impaired glucose tolerance in mice by repressing some components of the insulin-PI3K-mTOR pathway, such as IR, IRS2, PI3K interacting protein 1, Akt2, tuberous sclerosis complex 1, and rapamycin-insensitive companion of mTOR." (PMID 36674935, 2023). "The remaining loci were associated with ISI, including 6 loci not previously implicated in post-challenge insulin resistance: MTOR, COBLL1, PPARG, C5orf67, FAM101A, SLC2A4." (PMID 37291194, 2023). "Insulin resistance inhibits the PI3K/AKT/mTOR pathway in cancer cachexia." (PMID 36105371, 2022). "Moreover, insulin resistance with dysregulated insulin signaling can activate the PI3K/Akt/mTOR and Ras/Raf/MAPK pathways." (PMID 35276833, 2022). "Furthermore, the HCV core protein induces insulin resistance by altering protein phosphorylation with the subsequent alteration of the mTOR/S6K1 pathway and glucose uptake." (PMID 36560766, 2022). "Evidence for a role of BCAA in mTOR signaling and insulin resistance in humans is scarce." (PMID 35931683, 2022). "We hypothesize that CXCR4 antagonists may simultaneously inhibit MAPK, PI3k/AKT, and mTOR signaling pathway, inhibit cholesterol metabolism, and correct insulin resistance, which may exert a stronger inhibitory effect on the BCR signaling pathway." (PMID 35774848, 2022). "In turn, the increased circulating BCAA levels experienced by obese individuals may lead to hyperactivation of the mTOR pathway that worsens systemic insulin resistance and KLF15 transcription, thus forming a vicious cycle." (PMID 35634382, 2022). "This reinforces our hypothesis that BC2000 promotes the conversion of EA to urolithin A, which regulates autophagy clearance by modulating P13K/AKT/mTOR signaling, thereby slowing down the prevention of high-fat-induced insulin resistance in mice." (PMID 36235858, 2022). "In addition, the excess of BCAAs is associated with the imbalance of key neurotransmitters, with neural oxidative stress and apoptosis and with the mTOR hyperactivation that leads to brain insulin resistance." (PMID 35409380, 2022).